POLDIP3 (DNA polymerase delta interacting protein 3)
Description:
Is involved in regulation of translation. Is preferentially associated with CBC-bound spliced mRNA-protein complexes during the pioneer round of mRNA translation. Contributes to enhanced translational efficiency of spliced over nonspliced mRNAs. Recruits activated ribosomal protein S6 kinase beta-1 I/RPS6KB1 to newly synthesized mRNA. Involved in nuclear mRNA export; probably mediated by association with the TREX complex.
Synonyms: SKAR; KIAA1649; PDIP46; PDIP3
Tractability: PROTAC: UniProt records ubiquitination sites on it; ubiquitination databases record sites on it; its protein half-life has been measured.
Gene: Protein-coding gene on chromosome 22 (42,583,717 to 42,614,962, reverse strand). Ensembl gene ENSG00000100227.
Subcellular location: Nucleus; Nucleus speckle; Cytoplasm
Subcellular location (Human Protein Atlas): Nuclear speckles; Cytoplasmic bodies
Pathways (Reactome):
Metabolism of RNA: Transport of Mature mRNA derived from an Intron-Containing Transcript; mRNA 3'-end processing
Gene Ontology:
Molecular function: protein binding; protein-containing complex binding; RNA binding; nucleic acid binding
Biological process: poly(A)+ mRNA export from nucleus; positive regulation of translation; mRNA export from nucleus
Cellular component: cytoplasmic ribonucleoprotein granule; nuclear speck; cytoplasm; cytosol; nucleoplasm; transcription export complex; nucleus
Genetic constraint (gnomAD): Loss-of-function variants: 14 observed, 44.24 expected, observed/expected ratio (o/e) 0.32, 90% interval 0.21 to 0.5. The upper end of that interval is the gene's LOEUF score, 0.5, which puts it in group 2 of 6, group 1 being the genes least tolerant of losing a copy. Missense variants: 508 observed, 559.03 expected, observed/expected ratio (o/e) 0.91, 90% interval 0.84 to 0.98. Synonymous variants: 222 observed, 214.86 expected, observed/expected ratio (o/e) 1.03, 90% interval 0.93 to 1.15.
Homologues: Orthologues: chimpanzee POLDIP3 (99% identical), macaque POLDIP3 (98% identical), pig POLDIP3 (95% identical), mouse Poldip3 (91% identical), rat Poldip3 (91% identical), rabbit POLDIP3 (90% identical), guinea pig POLDIP3 (88% identical), tropical clawed frog poldip3 (66% identical), zebrafish poldip3 (49% identical), Drosophila melanogaster CG6961 (25% identical), Drosophila melanogaster CG18259 (25% identical), Caenorhabditis elegans aly-3 (9% identical), and 1 more. Paralogues in human: ALYREF (18% identical), CHTOP (10% identical).
Diseases named in the same sentence as POLDIP3 in open-access papers:
POLDIP3 is named in the same sentence as 17 diseases in open-access papers, as found by Europe PMC text mining. Sharing a sentence is not in itself a finding about the gene and the disease. The quoted sentences say what the papers report.
neuroblastoma (3 papers, 2015 to 2022). Neuroblastoma (NB) is the most common solid, extracranial childhood tumor. "Utilizing network-based microarray analysis and a visualization platform, researchers have found that a loss in POLDIP3 copy numbers leads to poor overall or recurrence-free survival in patients with neuroblastoma." (PMID 36425112, 2022). "Clinical outcome association analysis revealed a significant connection between POLDIP3 expression and overall and relapse-free survival in neuroblastoma patients." (PMID 36425112, 2022). "We silenced TDP-43 in two human cell lines representing neuronal and muscular cells — human neuroblastoma SH-SY5Y and rhabdomyosarcoma RH-3048, which resulted in exon skipping within POLDIP3." (PMID 35383280, 2022).
amyotrophic lateral sclerosis (1 paper, 2022). Amyotrophic lateral sclerosis (ALS) is a neurodegenerative disease characterized by progressive muscular paralysis reflecting degeneration of motor neurons in the primary motor cortex, corticospinal tracts, brainstem and spinal cord. "Studies have shown that the alternative splicing of POLDIP3 is related to amyotrophic lateral sclerosis (ALS)." (PMID 36425112, 2022).
breast carcinoma (1 paper, 2023). "Taken together, the AS events analyzed in COMMD4_AS2, EXOC7, RHOC, COMMD4_AS1 and POLDIP3 were related to a worse breast cancer prognosis, and could constitute potential prognosis biomarkers." (PMID 36725888, 2023). "In this study, we found a higher PSI value in breast cancer patients than in normal samples for COMMD4_AS2, GNAS, MATR3, RHOC and COMMD4_AS1, whereas the PSI value was lower for MARK3, POLDIP3 and FASTK." (PMID 36725888, 2023). "We found that METTL3 depletion promoted exon inclusion of the alternative exons of GNAS, MATR3, POLDIP3 and promoted skipping of the alternative exons of COMMD4, MARK3 and the non-m6A modified transcripts FASTK and EXOC7 in both breast cancer cell lines." (PMID 36725888, 2023). "We observed that the AS events for COMMD4_AS2, GNAS, MATR3,COMMD4_AS1 and RHOC displayed a significant higher PSI value in cancer patients than in normal samples, while the PSI values were significantly lower for MARK3, POLDIP3 and FASTK in patients with breast cancer." (PMID 36725888, 2023). "Although we found variabilities along the stages, which reflects the heterogeneity of this disease, COMMD4_AS2, MARK3, MATR3, POLDIP3, COMMD4_AS1, and GNAS underwent AS switches in almost all stages of breast cancer, while RHOC displayed significant AS switches during stage IIB." (PMID 36725888, 2023).
colon adenocarcinoma (1 paper, 2022). "The results have shown that IFN-α treatment can inhibit the growth of HT29, a malignant colon adenocarcinoma cell; this inhibition, however, is reversed by POLDIP3 knockdown." (PMID 36425112, 2022).
gastric cancer (1 paper, 2022). A primary or metastatic malignant neoplasm involving the stomach. "POLDIP3 can be used as a gene associated with gastric cancer protection and as part of a prognosis model composed of 10 genes to predict treatment response and prognosis in patients with gastric cancer." (PMID 36425112, 2022).
invasive breast carcinoma (1 paper, 2023). A carcinoma that infiltrates the breast parenchyma. "Additionally, COMMD4_AS1, GNAS, POLDIP3, FASTK, and RHOC AS were significantly associated with METTL3 deletion whereas AS of EXOC7 correlated with both deletion and gain of METTL3 in invasive breast carcinoma." (PMID 36725888, 2023).
virus infection (1 paper, 2023). "Therefore, we speculate that coronaviruses employ similar POLDIP3 cleavage mechanisms mediated by nsp5 to antagonize the host antiviral responses to sustain efficient virus infection." (PMID 37801439, 2023). "Collectively, we speculate that coronaviruses employ similar POLDIP3 cleavage mechanisms mediated by nsp5 to antagonize the host antiviral responses to sustain efficient virus infection, which deepened our better understanding of the mechanisms of coronaviruses infection." (PMID 37801439, 2023). "However, the regulatory effects of POLDIP3 in virus infection remains unclear." (PMID 37801439, 2023).
cancer (9 papers, 2015 to 2024). A tumor composed of atypical neoplastic, often pleomorphic cells that invade other tissues. "The catalogue of somatic mutations in cancer (COSMIC) database also showed that significant up- or down-regulation of POLDIP3 as being associated with various cancers as well as a number of mutations." (PMID 28737709, 2017). "Since the discovery of POLDIP3, relevant studies about POLDIP3 have mainly assessed its role in the occurrence of diverse diseases, including cancer." (PMID 37801439, 2023). "Relevant studies on POLDIP3 have mainly assessed its role in the occurrence of neurological diseases, immune diseases, and cancer." (PMID 36425112, 2022). "To further investigate the functions of POLDIP3 in vivo, we generated POLDIP3 genetic knockout (KO) using CRISPR/Cas9 technology in multiple cancer cell lines." (PMID 36360158, 2022). "Overall, our data highlight a previously unsuspected role of RTEL1 and Poldip3 in R-loop suppression at genomic regions where transcription and replication intersect, with implications for human diseases including cancer." (PMID 32561545, 2020).
infection (4 papers, 2016 to 2024). The state of being infected such as from the introduction of a foreign agent such as serum, vaccine, antigenic substance or organism. "Surprisingly, an antagonistic strategy was revealed that PDCoV encoded nonstructural protein 5 (nsp5) can reduce the POLDIP3 expression via its cleavage at the glutamine acid 176 (Q176), leading to enhanced PDCoV infection by disrupting the antiviral activity of POLDIP3." (PMID 37801439, 2023). "In addition, among 46 TRP32 target genes previously found to be differentially expressed during infection, 8 are also TRP47 targets, including CAP1, CMC1, HLX, ING1, MTFR2, NAT10, PARP16, and POLDIP3." (PMID 30408047, 2018). "Fifthly, nsp5 impairs porcine DNA polymerase delta interacting protein 3 (POLDIP3)-mediated antiviral effects by cleaving POLDIP3 at Q176 via its 3C-like protease activity in a manner independent of the proteasome and cellular autophagy pathways, ensuring efficient PEDV infection." (PMID 38793808, 2024).
immune diseases (2 papers, 2008 to 2022). "POLDIP3 as new autoantigens that could be used as markers in the diagnosis of immune diseases." (PMID 36425112, 2022). "POLDIP3 as a new autoantigen that could be used to diagnose immune diseases." (PMID 36425112, 2022). "We identify four nuclear proteins, HDAC5, TFC4, RTF1 and POLDIP3 polymerase as new autoantigens that could be used as markers in the diagnosis of subfamilies in immune diseases, although we cannot determine the role of these proteins in the aetiopathogenic process." (PMID 18625050, 2008).
POLDIP3 also shares sentences with these, for which no sentence is quoted: tumor (2 papers); dyskeratosis congenita (1); Hoyeraal-Hreidarsson syndrome (1); leukemia (1); liver cancer (1); neurological diseases (1); rhabdomyosarcoma (1).